MMP9 (matrix metallopeptidase 9)
Diseases named in the same sentence as MMP9 in open-access papers (continued):
Sharing a sentence is not in itself a finding about the gene and the disease.
tumor (continued). "Further, disruption of CD44/MMP-9 cluster formation had resulted in reduction of tumor invasiveness in vivo." (PMID 19290049, 2009). "The activity of MMP-2 and MMP-9 in the tumor tissue was also detected by the gelatin zymography assay." (PMID 19228418, 2009). "Duality of tumour MMP-9 levels with respect to survival has been recognised before in immunohistochemistry-based studies." (PMID 18506186, 2008). "These leukocytes produce cytokines, and growth and angiogenic factors, as well as matrix-degrading proteases (such as the matrix metalloproteinases MMP1, MMP3 and MMP9) and their inhibitors, which allow tumour cells to proliferate, invade and metastasise." (PMID 19050705, 2008). "The aim of this investigation was to evaluate the effect of berberine on MMP-9 expression and tumor cell invasion." (PMID 19052522, 2008). "These same studies performed in vitro, show that the use of salicylates decreases the invasive capacity of the tumor cell lines, as well as their MMP-9 secretion by blocking the NFkB signaling pathway." (PMID 18954439, 2008). "At the same time, tumor cells secrete MMP-2 and MMP-9 that degrade the matrix around the tumor and the nerve tissue, promoting PNI." (PMID 18983683, 2008). "MMP-9 plays a critical role in the recruitment of bone marrow derived CD45 positive cells into the primary tumor and the establishment of a mature vasculature." (PMID 19787098, 2008). "CXCL12 can induce tumor cell secretion of MMP-9 that then degrades the blood vessel basal membrane, remodels vessels and stimulates growth of new vessels." (PMID 18983683, 2008). "Similar analysis on our tumour MMP-9 data revealed that not only patients with the highest, but also those with the lowest levels had a worse survival than patients with intermediate levels." (PMID 18506186, 2008). "We therefore sought to examine the effects of curcumin on MMP-2, MMP-9, and uPA on tumor tissues derived from xenografted nude mice." (PMID 18226269, 2008). "Since MMP-3 can activate other MMPs involved in mediating tumor invasion, including MMP-9, the relationship between MMP-3 genotype, IPC, and gelatinase levels in end-of-assay CM was analyzed." (PMID 17922906, 2007). "Blocking MMPs activity specially MMP-2 and MMP-9 has been implicate to inhibit tumor invasion and angiogenesis." (PMID 19662219, 2007). "The roles of MMP2 and MMP9 in the regulation of tumor invasiveness and growth are well established in in vivo and in vitro animal models." (PMID 17567918, 2007). "The expression of MMP-9 or TIMP-2 by tumour cells, MMP-1, 7, 9, 11, 13, or TIMP-3 by fibroblastic cells, and MMP-7, 9, 11, 13, 14, TIMP-1, or TIMP-2 by mononuclear inflammatory cells, was also significantly associated with a higher rate of distant metastases." (PMID 17342087, 2007). "In this study, we demonstrated that MMP-2 and MMP-9 are produced predominantly by mesothelial cells and their expression is up-regulated once there is a contact between the mesothelial cells and the tumor cells." (PMID 19662219, 2007). "Confirmation of the protective effects of MMPs in cancer has come from animal experiments where tumours that arise from MMP-9 knockout (KO) mice were of a higher grade and displayed increased aggressiveness." (PMID 17311017, 2007). "The authors reported that, in three-dimensional environments, E-cadherin deficiency indeed led to a loss of intercellular adhesion and triggered tumor cell invasion by MMP-2 and MMP-9 driven matrix degradation." (PMID 17254360, 2007). "Matrix metalloproteinases -2 (gelatinase A) and MMP-9 (gelatinase B) are related to tumour invasion and metastasis by their special capacity to degrade the type IV collagen found in basement membranes, and to induce angiogenesis." (PMID 17342087, 2007). "It was shown recently that tumor metastatic activities is mediated by OPG/RANK/RANKL/MMP-9 signaling in PC3 cells and is inhibited by genistein." (PMID 17343740, 2007).
tumor (continued). "Release of MMP-9 enables tumor cells to invade through basement membranes of blood vessels and lymphatics, thereby initiating metastatic spread." (PMID 18093334, 2007). "As type IV collagen is one of the integral components of BM, the uncontrolled expression of two type IV collagenases, MMP-9, is believed to play a critical role in the invasion of BM by tumor cells." (PMID 18093334, 2007). "IFNα can repress VEGF and MMP-9 gene expression, endothelial cell functions, and, inhibit tumour-driven angiogenesis in vivo." (PMID 17958916, 2007). "MMP2 and TIMP2 were the major secretory proteins found in A549 tumour-conditioned medium, whereas MMP9 and TIMP1 were the key proteinases secreted by MDA-MB-231 cells." (PMID 16495926, 2006). "Both MMP2 and MMP9, which degrade type IV collagen, have been shown to increase expression in tumour cells and correlated with the malignant phenotype." (PMID 16495926, 2006). "Although MMP-2 null and MMP-9 null fibroblasts formed smaller tumors in vivo, the take rate for these fibroblasts in combination with tumor cells was 100% of injected animals." (PMID 16515711, 2006). "In the in vivo setting, both MMP-2 and MMP-9 null fibroblasts decreased FaDu tumor volume compared to wild-type fibroblasts, but MMP-2 and MMP-9 null fibroblasts promoted 100% tumor formation." (PMID 16515711, 2006). "Co-injection of FaDu tumor cells with fibroblasts in an orthotopic oral cavity SCID mouse model demonstrated a reduction of tumor volume using MMP-9 and MMP-2 null fibroblasts (48% and 49%, respectively) compared to WT fibroblasts." (PMID 16515711, 2006). "In situ hybridization was carried out for the ets variant ETV4 (PEA3) (23 cases) as well as MMP-9 (19 cases) and MMP-14 (13 cases), demonstrating high mRNA expression in the tumor cells." (PMID 16042759, 2005). "Matrix metalloproteinases, in particular the gelatinases MMP-2 and MMP-9, have received great attention in recent years as putative tumour markers for clinical applications." (PMID 15054465, 2004). "The mean MMP-9 activities of lysates extracted from psiCEACAM6-derived tumours were significantly lower than those of psiControl-derived tumours." (PMID 15316565, 2004). "MMP-9 expression was significantly correlated with the depth of tumour invasion (P=0.004), lymphatic permeation (P=0.001), nodal metastasis (P=0.049), and pathologic differentiation grade (P=0.003)." (PMID 14647147, 2003). "Coexpression of MMP-7 and MMP-9 was significantly correlated with deep tumour invasion in MM and SM (P=0.008), and positive nodal metastasis (P=0.008)." (PMID 14647147, 2003). "MMP-9 expression for the whole tumour was also related to the oesophageal tumour differentiation grade, along with depth of invasion, lymphatic permeation and nodal metastasis." (PMID 14647147, 2003). "On the other hand, expression of MMP-9 at the invasive front was significantly correlated with deep tumour invasion (P=0.001), positive lymphatic permeation (P=0.012), and positive nodal metastasis (P=0.047)." (PMID 14647147, 2003). "TIMP-1 availability should prevent formation of MMP-9 dimers, while we found high levels of the homodimer of MMP-9 (220 kDa) and the heterodimer of MMP-9 and NGAL (135 kDa), indicating that there is unbound MMP-9 left in tumour tissue." (PMID 12085179, 2002). "The active to proform ratio of MMP-2 is highest in tumour tissue, whereas this ratio for MMP-9 is highest in distant normal mucosa." (PMID 12085179, 2002). "Amounts of MMP-9 secreted per cell into serum-free tumour-conditioned medium from both lines was 2–3-fold higher for mock transfectants, compared with cells transfected with antisense β6." (PMID 12177807, 2002). "To specifically examine the role of β6-bound ERK2 on MMP-9 secretion we tested the ability of cells expressing a β6 deletion mutant that lacks the binding site for ERK2 to secrete MMP-9 into tumour-conditioned medium." (PMID 12177807, 2002).
tumor (continued). "In contrast, for MMP-9 the ratio was highest in normal mucosa and decreased (P<0.05) in the samples containing tumour tissue." (PMID 12085179, 2002). "In contrast to MMP-2, the proform of MMP-9 increases much more than active MMP-9 during normal to tumour conversion." (PMID 12085179, 2002). "In the present study, we show that down-regulation of constitutive β6 expression using an antisense approach against β6, that is known to suppress MAP kinase activity, dramatically reduced MMP-9 levels in tumour-conditioned medium." (PMID 12177807, 2002). "SW480 β6 transfectants not only secrete markedly more MMP-9 into tumour-conditioned medium than SW480 cells transfected with vector alone (mock transfectants) but this was inhibitable by the MEK-1 inhibitor, PD98059." (PMID 12177807, 2002). "Matrix degradation by MMPs is crucial for growth, invasion, metastasis and angiogenesis of tumours and increased tissue expression of MMP-9 has been observed in the progression from benign to malignant colonic epithelium." (PMID 12177807, 2002). "Real-time quantitative RT–PCR analysis was performed on mRNA transcripts of nine genes (VEGF121, VEGF165, VEGF189, VEGF-C, eIF-4E, b-FGF, TSP-2, MMP-2 and MMP-9) involved in angiogenesis and/or lymphangiogenesis as well as tumour cell invasion." (PMID 12189553, 2002). "During IL-12 therapy, tumour levels of the matrix metalloprotease MMP-9 declined and its inhibitor TIMP-1 was strongly induced." (PMID 11076665, 2000). "Elevated expression of type IV collagenases (MMP-2 and MMP-9) has been strongly correlated with tumour progression and metastasis in various tumours." (PMID 11044366, 2000). "The MMP-9 tumour to normal mucosa fold-increase (T/N) was 9.7 +/- 7.1 (mean +/- s.d.)(P < 0.001) for RNA and 7.1 +/- 3.9 (P < 0.001) for protein." (PMID 8883399, 1996). "Both MMP-9 mRNA and protein signals were strongest in the population of stromal cells concentrated at the tumour-stroma interface of an invading tumour." (PMID 8883399, 1996). "The sites of MMP-9 mRNA and protein synthesis were colocalised in tumour stroma by in situ hybridisation and immunohistochemistry in 26 CRC samples." (PMID 8883399, 1996). "Given the persistent localisation of MMP-9-producing macrophages to the interphase between CRC and surrounding stroma, our observations suggest that MMP-9 production is controlled, in part, by tumour-stroma cell interactions." (PMID 8883399, 1996). "Pro-MMP-9, in its 92 kDa form, was shown to be exclusively expressed by malignant prostatic tissue, and in particular by tumours that exhibited the aggressive and metastatic phenotype." (PMID 7506923, 1994). "In contrast, the high-risk group was enriched for CD66b+/MMP9+ (pro-tumor neutrophils), FAP+/collagen IV+ (extracellular-matrix-remodeling fibroblasts) and CD163+/MMP9+ (M2-like tumor-associated macrophages), reflecting distinct tumor microenvironments between the two groups." (PMID 41491099, 2026). "Furthermore, QUE downregulated the expression of key inflammatory factors (IL1β, CXCL8, and MMP9), inhibiting neutrophil activation and infiltration, as well as suppressing tumor growth in CRC." (PMID 41601690, 2026). "MMP-9 facilitates various stages of metastatic progression, encompassing EMT induction, enhanced cell migration, angiogenic activation, and the sustenance of tumor-associated inflammatory responses." (PMID 41596524, 2026). "Immunohistochemical analyses demonstrated markedly decreased matrix metalloproteinase (MMP) 2 and MMP9 positive areas in tumor tissues from HF-treated mice compared to controls, indicating profound suppression of matrix remodeling enzymes that are critical for invasion and metastasis." (PMID 41511301, 2025). "Suppress TAM production of VEGF/MMP9;Block tumor vascularization." (PMID 40264780, 2025).
tumor (continued). "In addition, single-cell sequencing experiments have reported that an increased MMP9 expression is correlated with decreased infiltration of cytotoxic CD8+ T cells into the tumor, as well as increased anti-PD-1 resistance in MSI-H/dMMR CRC patients." (PMID 41010517, 2025). "The anti-tumor effect of BV components may result from reducing the secretion of MMP-2 and MMP-9 into the extracellular space, thus reducing the potential ability to degrade the tissue surrounding the tumor." (PMID 40141020, 2025). "Moreover, IL-33 stimulates TAMs to produce high levels of MMP9 through activation of NF-κB, and MMP9 allows tumor cells to intravasate into the circulation." (PMID 40453088, 2025). "MMP-9 serves as a crucial molecule in various physiological functions, including reproduction and inflammation, but also assists cancer cells in spreading from the primary tumor." (PMID 40298802, 2025). "Our study revealed that MMP9 is significantly more expressed in tumor cells." (PMID 41562091, 2025). "Western blot analyses were subsequently performed to assess the effects of PTEs on the expression levels of matrix metalloproteinases 2 and 9 (MMP2 and MMP9), which are key mediators of cancer progression through their roles in promoting tumor invasion, metastasis, and angiogenesis." (PMID 40723276, 2025). "NE and MMP-9 cooperate to promote tumour migration and invasion." (PMID 41451221, 2025). "Moreover, expression levels of MMP2 and MMP9, known to play key roles in tumor metastasis, decreased following O+C treatment." (PMID 39859407, 2025). "In addition to MMP-2, MMP-9 has been extensively reported to promote tumor invasion and metastasis in CRC and other malignancies, while also playing a role in immune regulation." (PMID 40611940, 2025). "Moreover, in TNBC, histological MMP9 expression—particularly in residual post-chemotherapy tumor tissue—has been shown to predict disease-free survival, suggesting a context-specific predictive rather than prognostic role for MMP9 in this subtype." (PMID 40940762, 2025). "In contrast, the downregulation of TGF‐β and MMP‐9 is associated with inhibited matrix remodeling and invasiveness, which aligns with our functional experiments demonstrating that IFI30 knockdown contributes to tumor suppression." (PMID 40186402, 2025). "In another mGT case, Pabuççuoğlu and Lebe observed CD34 and MMP-9 expression, suggesting that MMP-9, produced by both tumor cells and mast cells, may contribute to the development of the myxoid stroma through extracellular matrix remodeling." (PMID 41300877, 2025). "IHC showed that the five markers, HYAL-1, HAS-2, N-Cadh, Slug, and MMP-9 included in the CM-6 signature, were upregulated in tumor tissues from patients who developed metastasis compared to normal colon tissues and in tumors from patients who did not develop metastasis." (PMID 40149256, 2025). "However, some research findings suggest that ketamine can reduce MMP‐9 synthesis, thereby inhibiting the formation of the tumor microenvironment before metastasis and restraining the proliferation and invasion of tumor cells." (PMID 40808216, 2025). "Moreover, MMP-9’s pivotal role in the tumor microenvironment, including angiogenesis and metastasis, complicates the complete inhibition of MMP-9-associated tumor progression by targeted therapies." (PMID 40284474, 2025). "In addition to their role in tumor angiogenesis, MDSCs secrete substances such as matrix metalloproteinase 9 (MMP9) and vascular endothelial growth factor (VEFG)." (PMID 40149640, 2025). "Additionally, ACT effectively downregulated the mRNA and protein expression levels of matrix metalloproteinase-9 (MMP-9), thus impeding tumor cell metastasis." (PMID 40722959, 2025). "Moreover, the newly induced SASP characteristics by IFI30 knockdown, including elevated levels of IL‐6, IL‐8, and TNF‐α, as well as decreased levels of TGF‐β and MMP‐9, reflect the dynamic interplay between senescence and tumor suppression." (PMID 40186402, 2025).
tumor (continued). "Meanwhile, integrin αvβ5 promotes VM formation by binding to vitronectin in the ECM and activating the FAK signaling pathways, which subsequently upregulate VEGFA and MMP9 expression, enhancing tumor cell migration, invasion, and the formation of tubular VM structures." (PMID 41019994, 2025). "CD20+ subpopulation, known to secrete cytokines and chemokines that activate the STAT3/NF-κB signaling pathway, leading to increased expression of pro-inflammatory mediators, including IL-6, TNF-and IFN-γ, and MMP-9, which facilitate tumor invasion and metastasis." (PMID 40821783, 2025). "Combining TCR‐T therapy with enhanced co‐stimulatory molecules, such as adhesion and accessory molecules, or modifying the tumour microenvironment (e.g., using MMP9 inhibitors), could potentially improve therapeutic efficacy." (PMID 40401927, 2025). "A reduction in MMP9 activity indicates that the complex 1 may be limiting the cancer cells’ invasive potential, thereby potentially hindering tumor progression." (PMID 40149886, 2025). "Therefore, the goal was to measure MMP-9 levels and examine their correlation with tumor mass and perilesional edema volumes." (PMID 41573658, 2025). "This further implies that MMP-9 release and its role in extracellular matrix remodeling may aid tumor progression." (PMID 41573658, 2025). "MMP2 and MMP9 are known to induce the dissemination of tumor cells." (PMID 40566630, 2025). "Several studies have demonstrated that MMP-9 is overexpressed in CaB patients compared with normal urothelial tissue and may be correlated to clinical prognostic factors such as high tumor pathological grade and size, stage, and progression." (PMID 41273852, 2025). "Taken together, Mir34aΔMye neutrophils show an increased expression of the miR-34a target Mmp9, which could contribute to the promotion of tumor progression and invasion." (PMID 39425000, 2025). "Increased tumorigenicity and metastatic potential were detected when these cells were implanted into mice bladders, suggesting that upregulation of MMP-9 may induce invasive tumor growth and metastasis." (PMID 41273852, 2025). "Within the tumour microenvironment, NETs can facilitate invasion into surrounding tissues and metastasis by degrading extracellular matrix components through proteins NE and matrix metalloproteinase-9 (MMP-9)." (PMID 40429915, 2025). "As a matrix metalloproteinase, MMP9 inhibitors can prevent tumor cell invasion and metastasis." (PMID 40170854, 2025). "MMP-9 promotes tumor development and progression in most cases, and in some specific cases may also play a suppressive role in tumor progression." (PMID 40391215, 2025). "In addition, overexpression of MMPs has been observed frequently in the context of SCCs, where a high proportion of MMP‐9 was shown to be expressed by tumor keratinocytes as well as tumor‐infiltrating immune cells." (PMID 39853777, 2025). "For example, MMP-9 cleavage can facilitate deeper tumor penetration and enhance permeability." (PMID 40284474, 2025). "Suppressive immune cells and molecules in the tumour microenvironment, including M2 macrophages and matrix metalloproteinase 9 (MMP9), can impair the function of TCR‐T cells, while chronic antigen exposure may induce T cell exhaustion." (PMID 40401927, 2025). "Particularly relevant to anoikis resistance, MMP9 regulates EMT through the PI3K/AKT/NF-κB signalling pathway—a critical connection since EMT has been established as not only essential for tumour invasion but also a key feature in anoikis resistance development." (PMID 40830065, 2025). "However, in the presence of MMP-9, which is often present in the tumor microenvironment, cleavage of the linker can fully regenerate the cytosolic cargo delivery capabilities, resulting in MMP-9-specific cytosol penetration." (PMID 39895690, 2025). "The MMP-9 levels correlated with Ki-67, suggesting its role in tumor proliferation." (PMID 40265458, 2025).